BRAF (B-Raf proto-oncogene, serine/threonine kinase)
Diseases named in the same sentence as BRAF in open-access papers (continued):
Sharing a sentence is not in itself a finding about the gene and the disease.
pituitary tumor (5 papers, 2017 to 2021). A benign or malignant neoplasm affecting the pituitary gland. "However, it has first to be shown that pituitary tumors indeed develop in the latter models (in analogy with BRAF mutations in humans)." (PMID 29255445, 2017). "Hence, BRAF p.V600E can lead to two pathologically distinct types of pituitary tumours, most probably depending on the pituitary cell type of origin from which the mutation arises." (PMID 33795686, 2021). "No BRAF mutation was found in either the thyroid or pituitary neoplasms of the patient diagnosed with MTC." (PMID 29593792, 2018).
plasmacytoma (5 papers, 2015 to 2025). Plasmacytoma is a localized mass of neoplastic monoclonal plasma cells that represents approximately 5% of all plasma cell neoplasms. "We have measured KRAS, NRAS, and BRAF gene mutations in circulating free tumor DNA (ctDNA) from plasma, bone marrow, and plasmacytoma samples as well as their correlation with various clinical and laboratory parameters." (PMID 40943426, 2025). "The frequency of the KRAS, NRAS, and BRAF gene mutations in any of the tumor substrate (bone marrow, ctDNA, plasmacytoma) in the entire group was 50% (56 out of 113)." (PMID 40943426, 2025). "Mutations in the KRAS, NRAS, and BRAF genes either in bone marrow, ctDNA, or plasmacytoma samples were found in 50% of patients." (PMID 40943426, 2025). "Prior to CAR-T therapy, targeted and WES had identified a BRAF(V600E) mutation in his BM, which persisted throughout treatment and was also detected in a cutaneous plasmacytoma with a variant allele frequency (VAF) of 41% at relapse from CAR-T." (PMID 35978321, 2022). "Here, we present an analysis of the STR profiles and mutation status of the KRAS, NRAS, and BRAF genes, evaluated in plasma free circulating tumor DNA (ctDNA), CD138+ bone marrow cells, and plasmacytomas." (PMID 39273371, 2024). "The mutation status of the KRAS, KRAS, and BRAF genes in ctDNA, CD138+ bone marrow cells, and plasmacytomas was analyzed by AS-PCR and NGS." (PMID 39273371, 2024). "Based on whole-exome sequencing, we identified a BRAF (V600E) dominant subclone in both bone marrow and cutaneous plasmacytoma." (PMID 35978321, 2022). "The presence of mutations in the KRAS, NRAS, and BRAF genes is more prevalent in the ctDNA of patients with plasmacytoma compared to those without." (PMID 40943426, 2025). "A principal finding of this work is that mutations in KRAS, NRAS, or BRAF genes within ctDNA were significantly more prevalent in patients with plasmacytoma compared to those without (28% vs. 0, p = 0.0007)." (PMID 40943426, 2025). "In the 11 extramedullary plasmacytomas, mutations were detected in the NRAS gene in 27% of cases (n = 3) and in the BRAF gene in 18% (n = 2), suggesting a tendency for KRAS mutations to be more frequent in bone lesions, while NRAS mutations were more common in extramedullary sites." (PMID 40943426, 2025).
prostate adenocarcinoma (5 papers, 2008 to 2025). "Taken together, these observations indicate that, while sustained BRAF* activation in the prostate gland is sufficient to drive development of invasive prostate adenocarcinoma, it is not required for maintenance of established PCA." (PMID 19079609, 2008).
salivary duct carcinoma (5 papers, 2017 to 2026). An aggressive, high grade adenocarcinoma that arises from the salivary glands. "One patient with a high grade salivary duct carcinoma with a BRAF driver mutation had a near complete response to a combination of BRAF and MEK inhibitors for over 12 months." (PMID 28915716, 2017). "Two BRAF alterations were identified in patients with adenoid cystic carcinoma and salivary duct carcinoma." (PMID 35267442, 2022).
skin squamous cell carcinoma (5 papers, 2014 to 2024). A carcinoma arising from the squamous cells of the epidermis. "Acquired resistance and development of secondary squamous cell skin cancers and other skin toxicities associated with BRAF inhibitors caused by the paradoxical activation of wild-type BRAF kinase in the MAPK pathway in normal tissues were the challenges faced with BRAF inhibitor monotherapy." (PMID 38203795, 2024). "The addition of MEK inhibitors to BRAF inhibition could delay the development of this acquired resistance by blocking ERK signaling as well as prevent paradoxical MAPK pathway activation in the development of secondary squamous cell skin cancers, hence the development of combination treatments." (PMID 38203795, 2024).
small bowel adenocarcinoma (5 papers, 2021 to 2024). "Studies have also shown that the majority of BRAF mutations in small bowel adenocarcinoma are non-V600E, which is consistent with our current report." (PMID 38791902, 2024). "BRAF mutations are rare in small-bowel adenocarcinoma (7.6%), only 10% of the observed mutations corresponding to V600E and a majority of the others being inactivating mutations." (PMID 33530449, 2021). "BRAF V600E mutation has never been described in NADAs, while it may be present in up to 10% of BRAF-mutated small bowel adenocarcinomas." (PMID 33922305, 2021).
spinal astrocytomas (5 papers, 2019 to 2022). "Here, we also found that BRAF V600E only occurred in H3-wildtype grade II/III spinal cord astrocytomas, and was associated with a good prognosis." (PMID 32228694, 2020). "One prior report demonstrated mutations in p16 (chromosome 9p21), PTEN (chromosome 10q23) and BRAF in spinal astrocytomas, although tumors were analyzed in combination with other midline PAs37." (PMID 31822682, 2019). "Grade II spinal astrocytomas appear to harbor BRAF-KIAA1549 translocations and BRAF amplifications." (PMID 34685506, 2021).
Splenomegaly (5 papers, 2021 to 2025). Abnormal increased size of the spleen. "SMZL, while similarly involving splenomegaly and cytopenias, is characterized by circulating villous lymphocytes and lacks both the BRAF BRAF V600E mutation and the immunophenotypic profile of HCL." (PMID 40421333, 2025). "Given the clinical findings of neutropenia, anemia, thrombocytopenia, and splenomegaly, coupled with the presence of hairy cells in blood film and bone marrow, as well as positivity for CD11c, CD25, and the BRAF mutation, the patient was diagnosed with HCLc." (PMID 40687069, 2025). "Zhao and colleagues reported a similar case of a patient who presented with fatigue, pancytopenia with monocytopenia, and splenomegaly and was diagnosed with CD103-negative and CD23-positive HCLc, alongside a positive BRAF V600E mutation." (PMID 40687069, 2025).
synovial sarcoma (5 papers, 2021 to 2026). "Unfortunately these targetable mutations appear to be very rare in sarcomas, with clinical-grade panel sequencing of 259 synovial sarcomas failing to reveal any bearing BRAF V600E mutations." (PMID 40849585, 2025). "BRAF V600E mutations have been reported in three patients with thoracic synovial sarcoma, two of whom demonstrated transient clinical responses to BRAF/MEK inhibitors." (PMID 40849585, 2025). "One female patient in her 20s diagnosed with synovial sarcoma was found to have BRAF V600E mutation from a prior tissue NGS test and had received dabrafenib plus trametinib." (PMID 34900683, 2021). "This suggests that BRAF V600E is a potential therapeutic target for a small subset of patients with synovial sarcoma, and it warrants screening given the encouraging tumour-agnostic activity of the combination of dabrafenib with trametinib and its tumour-agnostic regulatory approval." (PMID 39796641, 2024).
transitional cell carcinoma (5 papers, 2019 to 2025). A malignant neoplasm arising from the transitional epithelium, usually affecting the urinary bladder, ureter, or renal pelvis. "This is the first study to utilise AI histology to predict BRAF mutational status in canine urothelial cell carcinomas." (PMID 37570213, 2023). "Interestingly, the sequencing analysis of BRAF in canine transitional carcinoma cells revealed a close homology to human BRAF and that its mutations commonly result in increased MAPK pathway activity in both human and canine tumors." (PMID 40563676, 2025). "Detecting BRAF mutations from urine using ddPCR offers a valuable option if the histological or cytological diagnosis of transitional cell carcinoma remains unclear and can even be used as a screening test in predisposed breeds, such as Terriers." (PMID 39591358, 2024). "The presence of BRAF variant V595E, as well as an increased cyclooxygenase-2 (COX-2) expression in canine transitional cell carcinoma (TCC) are well-described in the literature." (PMID 30893857, 2019). "In this regard, the in vitro growth of several BRAF-mutated canine transitional carcinoma cell lines was not inhibited by the BRAF inhibitor vemurafenib, whereas MAPK inhibitors do so similarly to human BRAF-mutant cell lines." (PMID 40563676, 2025).
vaginal melanoma (5 papers, 2015 to 2025). A primary malignant neoplasm of the vagina composed of malignant melanocytes. "The other two BRAF mutation patients were both stage III vaginal melanomas and received corresponding immunotherapy after confirming the mutation." (PMID 40933889, 2025). "Only one BRAF mutation was identified, demonstrating the superiority of ICIs over BRAF inhibitors in treating vaginal melanoma." (PMID 38289480, 2024). "BRAF mutation was present in 26% of patients with vulvar and vaginal melanoma; however, only half of them were V600 mutations, which significantly reduces the effectiveness of BRAF and MEK inhibitors therapy typically used in CM." (PMID 37679999, 2023). "Previous studies showed that BRAF was mutated in 0 to 33% of patients with vulvar and vaginal melanomas with sample sizes ranging from 1 to 51 cases." (PMID 34102999, 2021). "Among the four tested vaginal melanoma patients, two had BRAF mutations." (PMID 40933889, 2025). "Notably, only some of the BRAF-mutant vulvar and vaginal melanomas in the literature harbored BRAF V600E mutations." (PMID 34102999, 2021). "Specifically, in a study involving 30 patients with vulvar and vaginal melanomas, BRAF and NRAS mutations exhibited a 7% and 10% frequency, respectively, while similar low frequencies of BRAF mutation ranging from 0% to 12.5% have been detected in other studies." (PMID 25695059, 2015). "Of interest, the patient's vaginal melanoma harboured wildtype BRAF, which infers that BRAF inhibition would not be effective." (PMID 37679999, 2023).
acinar cell carcinoma (4 papers, 2015 to 2025). "In our case, the patient’s metastatic acinic cell carcinoma was found to harbor a BRAF mutation, which occurs in approximately 4–5% of all acinic cell carcinomas." (PMID 40622477, 2025). "In a retrospective case series of PDAC and acinar cell carcinoma, two patients with BRAF V600E mutations achieved a partial response on combined BRAF/MEK inhibition." (PMID 36551707, 2022). "In addition, a patient with acinar cell carcinoma in the tail of the pancreas and BRAF V600E mutation obtained 8 months of PFS by combined target therapy with dabrafenib and trametinib, but the patient received chemotherapy for more than 5 years before the target therapy." (PMID 35145907, 2021). "This molecular alteration offers the opportunity to use a BRAF inhibitor for treatment; however, the prognostic or therapeutic value of BRAF mutations has not been established in acinic cell carcinoma." (PMID 40622477, 2025).
adenosquamous carcinoma (4 papers, 2011 to 2023). A carcinoma composed of malignant glandular cells and malignant squamous cells. "In contrast, somatic mutations in BRAF were identified in 1 (2.1%) of 48 adeno/adenosquamous cell carcinomas." (PMID 21730982, 2011). "Somatic mutations in either KRAS or BRAF were identified in 4 (8.3%) of 48 adeno/adenosquamous cell carcinomas." (PMID 21730982, 2011). "The frequencies of KRAS and BRAF mutations were very low in both squamous and adeno/adenosquamous cell carcinomas." (PMID 21730982, 2011). "The key inclusion criteria are as follows: histologically diagnosed with colorectal adeno/adenosquamous carcinoma; RAS wild-type and BRAF V600E mutation by tissue or blood; and previously untreated resectable distant metastases." (PMID 37605122, 2023).
Arrhythmia (4 papers, 2016 to 2023). Any cardiac rhythm other than the normal sinus rhythm. "•AF is the most commonly reported arrhythmia associated with BRAF inhibitor/MEK inhibitor with an incidence of 1% to 4%." (PMID 35492830, 2022). "Further, immunotherapy is typically preferred in patients with a history of heart arrhythmias, given the potential cardiac risks with BRAF-MEK inhibitors." (PMID 37627153, 2023). "Systematic capture and reporting of arrhythmias are not common in clinical trials of BRAF inhibitor/MEK inhibitor; therefore, good data on this adverse effect are lacking." (PMID 35492830, 2022).
atrial fibrillation (4 papers, 2019 to 2025). A disorder characterized by an electrocardiographic finding of a supraventricular arrhythmia characterized by the replacement of consistent P waves by rapid oscillations or fibrillatory waves that vary in size, shape and timing and are accompanied by an irregular ventricular response. "There is a demonstrable risk of myocardial infarction, atrial fibrillation, and QTc prolongation with BRAF inhibitor therapy which is theorized to be caused by a BRAF-mediated alteration of the myocardial repolarization process." (PMID 36185227, 2022). "The RRs of myocardial infarction, atrial fibrillation, and QTc interval prolongation were similar between the BRAF and MEK inhibitor group and the BRAF inhibitor monotherapy control group." (PMID 31397860, 2019). "The RR of high-grade myocardial infarction, atrial fibrillation, and QTc interval prolongation were similar between the BRAF and MEK inhibitor group and the control group." (PMID 31397860, 2019).
autoimmune thyroid disease (4 papers, 2014 to 2025). Inflammatory disease of the thyroid gland due to autoimmune responses leading to lymphocytic infiltration of the gland. "Total thyroidectomy (TT) was performed in case of concurrent bilateral goiter, autoimmune thyroid disease, and/or presence of BRAF and/or RAS mutation." (PMID 32351561, 2020). "The relative paucity of high-risk molecular alterations (e.g., BRAF^V600E) and the presence of a distinct immunoregulatory microenvironment in HT-PTC underscore the potential protective influence of thyroid autoimmunity." (PMID 40563614, 2025).
carcinoid (4 papers, 2015 to 2025). "Specifically, in the first case a BRAF p.Val600Glu mutation in both adenocarcinoma and carcinoid components was documented." (PMID 34926584, 2021). "Increasing molecular evidence supports the composite lesions hypothesis: shared alterations, such as KRAS, NF1, and BRAF V600E mutations, have been reported in both adenocarcinoma and carcinoid components, suggesting a monoclonal origin in select cases." (PMID 41209982, 2025). "None of the BRAF, KRAS, NRAS, or PIK3CA mutations were detected in the carcinoid tumors; moreover, none of the 56 cases exhibited MSI-high status." (PMID 26090613, 2015). "We did not detect KRAS, BRAF, or PIK3CA mutations or MSI-high in the carcinoid tumors." (PMID 26090613, 2015).
chronic myelomonocytic leukemia (4 papers, 2022 to 2026). A myelodysplastic/myeloproliferative neoplasm which is characterized by persistent monocytosis, absence of a Philadelphia chromosome and BCR/ABL fusion gene, fewer than 20 percent blasts in the bone marrow and blood, myelodysplasia, and absence of PDGFRA or PDGFRB rearrangement. "The BRAFV600E-mutated patients also had myeloproliferative neoplasm (three chronic myelomonocytic leukemia and one JAK2-mutated essential thrombocythemia) compared to the BRAF wild-type group (36% vs. 0%; p = 0.046)." (PMID 37809108, 2023).
clear cell carcinoma (4 papers, 2012 to 2019). "Histologically, type I tumors would consist of low-grade micropapillary serous carcinoma, mucinous, endometrioid, and clear cell carcinomas and would be associated with mutations in KRAS, BRAF, PTEN, and beta-catenin." (PMID 22581446, 2012).
diffuse intrinsic pontine glioma (4 papers, 2020 to 2022). A neuroglial tumor that arises from the middle portion of the brain stem. "Based on these alterations, four pediatric HGG subtypes can be distinguished: H3.3-K27M; H3.1-K27M, characteristic of high grade midline gliomas, including diffuse intrinsic pontine glioma (DIPG); H3.3G34-R/V; and BRAF-V600E." (PMID 33790740, 2021).
Eosinophilia (4 papers, 2014 to 2025). "In both cases, sclerosing mucoepidermoid carcinoma with eosinophilia was positive for the BRAF V600E mutation by polymerase chain reaction." (PMID 31882020, 2019). "BRAF mutation studies were performed on the sclerosing mucoepidermoid carcinoma with eosinophilia tumors." (PMID 31882020, 2019).
Ewing sarcoma (4 papers, 2014 to 2024). A small round cell tumor that lacks morphologic, immunohistochemical, and electron microscopic evidence of neuroectodermal differentiation. "In a study of genetic changes in Ewing sarcoma, the strong, positive expression of BRAF (defined as a staining score greater than or equal to 100) was only 3%, suggesting that BRAF inhibitors have limited application in Ewing sarcoma." (PMID 32476297, 2020).
gastric tumor (4 papers, 2013 to 2020). "Histological and molecular analysis of the gastric tumor also indicated the presence of a BRAF V600E mutation." (PMID 30719207, 2019). "This study primarily focused on gastric tumors, and it included a limited number of small intestinal GISTs (6 of 75) as well as rare genotypes (NF1 and BRAF)." (PMID 33048845, 2020).
goiter (4 papers, 2016 to 2025). Enlargement of the thyroid gland usually caused by lack of iodine in the diet, hyperthyroidism, or thyroid nodules. "To conclude, an overall low level of statistical evidence exists regarding poorly differentiated malignancy in substernal goiters, and the data also remains scarce regarding the impact of genetic and molecular configurations, such as the BRAF-positive profile, in this specific instance." (PMID 40870901, 2025). "In one of these cases (sample #123, which was twice classified as a goiter), BRAF(V600E) was found, which is typically absent from the benign nodules." (PMID 26960768, 2016).
hereditary colorectal cancer (4 papers, 2014 to 2022). "Additional criteria, such as more comprehensive family histories and genetic tests, including BRAF V600E mutation and hypermethylation of the MLH1 promoter, are necessary to differentiate between sporadic and hereditary colorectal cancer." (PMID 34441055, 2021).
hereditary non-polyposis colorectal cancer (4 papers, 2006 to 2014). "Testing for BRAF mutation is beneficial in judicious selection of patients for targeted therapy and also a cost effective approach in the HNPCC (Hereditary Non-polyposis Colorectal Cancer) workup; presence of BRAF mutation with absence of MLH1 protein is indicative of sporadic CRC." (PMID 25005754, 2014). "In addition, BRAF V600E mutation is associated with sporadic microsatellite instable CRC, but not hereditary non-polyposis colorectal cancer (HNPCC) syndrome." (PMID 24252159, 2013). "Interestingly, BRAF mutations are found only in MSI+ sporadic tumors that result from aberrant MLH1 promoter methylation and do not occur in MSI+ tumors from hereditary non-polyposis colorectal cancer (HNPCC) patients, thus providing a convenient discriminator between sporadic and familial cases." (PMID 16403224, 2006).
Hyperglycemia (4 papers, 2017 to 2025). An increased concentration of glucose in the blood. "The ubiquitous nature of the BRAF/MAPK/MEK pathway means such treatments are not without side effects such as renal tubulopathies and hyperglycaemia." (PMID 39671021, 2025).